VWF (von Willebrand factor)
Diseases named in the same sentence as VWF in open-access papers (continued):
Sharing a sentence is not in itself a finding about the gene and the disease.
Hypomagnesemia (2 papers, 2015 to 2022). An abnormally decreased magnesium concentration in the blood. "Increased von Willebrand factor, hypomagnesemia and damage to the vascular endothelium are known risk factors for the cisplatin-associated vascular toxicity." (PMID 25621071, 2015). "The cause has been hypothesized to be endothelial damage, elevation of plasma levels of von Willebrand factor, drug-induced reduction of left ventricular function, or hypomagnesemia, although exact causes have yet to be confirmed." (PMID 35461358, 2022).
inflammatory bowel disease (2 papers, 2018 to 2025). A spectrum of small and large bowel inflammatory diseases of unknown etiology. "Research has reported increased release of VWF in the inflamed colonic tissue of patients with inflammatory bowel disease (IBD) and chronic mouse colitis models, with VWF levels being higher during active phases compared to remission." (PMID 40607383, 2025). "The van Willebrand factor (vWF, band A) is involved in the intrinsic coagulation pathway and the acute phase response and known to be increased in inflammatory bowel disease and bacterial diarrhea." (PMID 29459849, 2018).
influenza infection (2 papers, 2019 to 2022). "In vitro, VWF-induced platelet desialylation could be circumvented by the neuraminidase inhibitor oseltamivir acid, which is widely used worldwide in the treatment of influenza infections." (PMID 30849118, 2019). "Although vWF and ICAM-1 are upregulated during influenza infection, platelet adhesion to influenza-infected endothelial cells is primarily mediated by other molecules, such as endothelial fibronectin and platelet α5β1." (PMID 35419008, 2022).
insomnia (2 papers, 2018 to 2023). A sleep disorder characterized by difficulty in falling asleep and/or remaining asleep. "Past research suggests that higher concentrations of von Willebrand factor (vWF), tau, and hyperphosphorylated tau (p-tau) can be detected in patients with OSA and/or insomnia, but no study has been conducted in patients with chronic issues from mTBI." (PMID 37095856, 2023).
interstitial lung disease (2 papers, 2024). A diverse group of lung diseases that affect the lung parenchyma. "Candidate biomarkers CXCL9, GDF15, and vWF have previously been shown to correlate with global JDM activity, and WFDC2 and TNFSF13 have been associated with interstitial lung disease in DM." (PMID 39529136, 2024).
intimal sarcoma (2 papers, 2014 to 2019). A malignant neoplasm arising from the large blood vessels. "Vimentin is frequently positive in intimal sarcoma, whereas vascular markers such as CD31, CD34, vWF, and smooth muscle cell markers such as desmin are usually negative." (PMID 30925179, 2019).
kidney cancer (2 papers, 2020 to 2025). Primary or metastatic malignant neoplasm involving the kidney. "Increased expression of the VWF gene with respect to normal tissue was noted in a meta-analysis of kidney cancer expression data." (PMID 31936274, 2020).
leiomyosarcoma (2 papers, 2014 to 2015). An uncommon, aggressive malignant smooth muscle neoplasm, usually occurring in post-menopausal women. "Similar results were obtained for leiomyosarcoma and MFH: using an anti-vWf (von-Willebrand factor) staining to identify the microvessels, the authors confirmed what had been proposed in the previous studies." (PMID 25236925, 2014).
Lewis Lung Carcinoma (2 papers, 2021 to 2022). "For example, oral administration of AKG to mice grafted with tumor of Lewis Lung Carcinoma (3LL) caused a reduction in the spread of mitosis and the presence of tumors with von Willebrand factor (vWF), the marker of tumor vascular endothelium, therefore signifying the AKG’s antiangiogenic effect." (PMID 35323486, 2022).
lymphangioma (2 papers, 2019 to 2024). A benign lesion composed of dilated lymphatic channels. "Immunohistochemically, D2-40 is a specific marker for lymphangioma, while CD31, CD34, von Willebrand factor, and VEGFR3 can also be helpful for diagnosis." (PMID 39411124, 2024).
malignant glioma (2 papers, 2016 to 2017). A grade III or grade IV glioma arising from the central nervous system. "VWF expressing U251 malignant glioma cells also exhibited methylation levels at the +119 site that were similar to HUVEC." (PMID 28035064, 2017). "CAM assay of U251 cells demonstrated that in these VWF expressing malignant glioma cells VWF knockdown also significantly reduces extravasation." (PMID 28035064, 2017). "Various levels of VWF mRNAs were detected by quantitative RT-PCR in malignant glioma and SAOS2 cell lines, but not in any detectable levels in KHOS, or proximal tubule epithelial cells (PTEC) used as negative control." (PMID 28035064, 2017). "VWF expression was also demonstrated by immunofluorescence staining in SAOS2 and a representative patient derived malignant glioma cell line M049, but not in KHOS." (PMID 28035064, 2017).
Mitral regurgitation (2 papers, 2021 to 2023). An abnormality of the mitral valve characterized by insufficiency or incompetence of the mitral valve resulting in retrograde leaking of blood through the mitral valve upon ventricular contraction. "There are reports of moderate or severe native mitral regurgitation to be associated with abnormal VWF multimers and clinically significant GI bleeding, which reversed after mitral valve surgery." (PMID 37143635, 2023). "High‐molecular‐weight vWF multimer abnormalities have been reported in patients with different valvular diseases e.g. aortic and mitral valve stenosis as well as mitral valve regurgitation." (PMID 33372698, 2021). "In this largest investigation of AvWS in patients with mitral regurgitation so far, performing TMVR did not alter vWF levels or vWF activity 4 weeks after the procedure." (PMID 33372698, 2021).
morbid obesity (2 papers, 2022 to 2026). An excess of body weight, normally defined as an individual with a body mass index greater than 35 or a body weight greater than one hundred percent of ideal body weight. "Importantly, the newly reported individuals expand dominant STT3A-CDG with previously unreported features, including anorectal malformation, morbid obesity, and clinically significant bleeding diathesis with von Willebrand factor and factor VIII deficiency." (PMID 41897354, 2026).
Multiple Organ Failure (2 papers, 2015 to 2020). A progressive condition usually characterized by combined failure of several organs such as the lungs, liver, kidney, along with some clotting mechanisms, usually postinjury or postoperative. "Similarly, vWF did not predict the development of multiple-organ failure or mortality in 100 patients with ARDS; however, elevated plasma VWF levels did predict both the severity and mortality in 559 patients with ARDS." (PMID 33379178, 2020).
myeloma (2 papers, 2024 to 2025). "The increase in FVIII and VWF (VWF:Ag and VWF:Ac) during the IVIG test indicates the possibility of IVIG administration inhibiting the quantitative clearance mechanism by macrophages observed in most type 1 AVWS during myeloma, despite the normal VWF:pp/VWF:Ag ratio." (PMID 39228434, 2024). "This indirect effect could influence coagulation and VWF production regulation, unlike anti-myeloma treatments that target malignant plasma cells directly." (PMID 40277845, 2025).
Myocardial fibrosis (2 papers, 2023 to 2025). "NETs can bind to endothelial cells through vWF and P-selectin, providing a scaffold for platelet, neutrophil and erythrocyte binding, which further leading to fibrin deposition and thrombosis, and aggravating myocardial fibrosis and vascular injury." (PMID 40792212, 2025).
paroxysmal AF (2 papers, 2014 to 2017). "Plasma markers (von Willebrand factor (vWf), soluble P-selectin (sPsel) and interleukin-6 (IL-6)) were measured by ELISA at three time points in 80 patients (62±10 years, 63% males, 41% paroxysmal AF) undergoing CA." (PMID 25390649, 2014). "In addition, patients with permanent or paroxysmal AF exhibited elevated levels of vWF." (PMID 28570705, 2017).
polycythemia (2 papers, 2019 to 2021). Abnormally high mass or concentration of red blood cells in the blood, either due to an increase in erythropoiesis or a decrease in plasma volume. "Three months after discharge, polycythemia still persisted and the level of vWF gradually decreased." (PMID 33496866, 2021). "At the time of writing, 3 months have passed since discharge, yet polycythemia persists and the level of vWF is gradually decreasing (platelet count and vWF activity: 2030 × 103 μL and 31% on POD 31 and 2571 × 103 μL and 19% on POD 51, respectively)." (PMID 33496866, 2021). "The surgery was uneventful, but the patient presented with severe polycythemia and vWF abnormalities postoperatively, which resulted in bleeding from the drain insertion site and wound, epistaxis, and hemorrhoidal bleeding." (PMID 33496866, 2021). "However, patients who cannot receive these medications preoperatively, because of medication allergy, adverse events, or drug resistance, have a high possibility of polycythemia, abnormalities of vWF, and severe bleeding tendency." (PMID 33496866, 2021).
prediabetes (2 papers, 2017 to 2024). "ADAMTS13 activity was also associated with incident prediabetes (defined on the basis of both fasting and non-fasting blood glucose) after adjustment for known risk factors (HR 1.11 [95% CI 1.03, 1.19]), while the VWF antigen level was not." (PMID 27787621, 2017). "Specifically, vWF and PAI-1 levels decreased after the 1-year lifestyle intervention in individuals with prediabetes, suggesting improved endothelial function." (PMID 39175055, 2024).
prion disease (2 papers, 2022 to 2023). A transmissible disease that is caused by a protein that is able to induce abnormal folding of normal cellular proteins, leading to characteristic spongiform brain changes, which are associated with neuronal loss without an inflammatory response. "VWF might associate with “complement and coagulation cascades”, “drug metabolism-other enzymes”, “neuroactive ligand-receptor interaction”, “PPAR signaling pathway”, and “prion disease”." (PMID 35757392, 2022). "Other noteworthy hub-hub genes, including CKM, RYR1, and VWF, presented lower expression in LDM tissue and have critical roles in metabolic pathways, oxytocin signaling pathway, ECM-receptor interaction, prion disease, and calcium signaling pathway." (PMID 37627391, 2023).
sarcoidosis (2 papers, 2020 to 2022). Sarcoidosis is a multisystemic disorder of unknown cause characterized by the formation of immune granulomas in involved organs. "We also found autoAbs against antigens that were reported to be highly expressed in the granulomatous tissue of sarcoidosis patients, such as von Willebrand factor (vWF) and ferritin heavy chain 1 (FTH1)." (PMID 32046322, 2020).
scleroderma (2 papers, 2008 to 2023). Scleroderma is a rare autoimmune connective tissue disorder characterized by abnormal hardening of the skin and, sometimes, other organs. "Von Willebrand factor (VWF) and Von Willebrand factor A domain containing 1 (VWA1) are responsible for platelet adhesion and clot formation and were more highly expressed in scleroderma compared to control, indicating possible causes for microvascular damage." (PMID 37443817, 2023).
seminoma (2 papers, 2010 to 2025). A radiosensitive malignant germ cell tumor found in the testis (especially undescended), and extragonadal sites (anterior mediastinum and pineal gland). "Angiogenesis of seminomas were evaluated by immunohistochemical assay using polyclonal antibody against Von Willebrand factor (vWF) and by calculating the means of MVD, vessels area and perimeters using computerized image analysis." (PMID 20509912, 2010). "Immunohistochemical staining with vWF was performed to confirm tumor cells invasion into lymphatic or blood vessels in canine seminomas." (PMID 20509912, 2010).
septic shock (2 papers, 2011 to 2020). Shock caused by infection; frequently caused by gram negative bacteria, although some cases have been caused by other bacteria, viruses, fungi, and protozoa; characterized by fever, chills, tachycardia, tachypnea, and hypotension. "In this prospective study, septic shock was associated with activation of pro-coagulant pathways such as vWF:Ag and ultra-large VWF multimers and consumption of anti-coagulant factors such as ATIII, protein C, and ADAMTS13 activities." (PMID 32122366, 2020). "In patients with septic shock and positive levels of GrM as quantified from western blot band intensities, the VWF/FVIII ratio was increased as compared to the other groups and controls (p<0.05)." (PMID 21909423, 2011). "Since GrM is elevated in septic shock patients and abolishes VWF binding to FVIII, one would expect an increase in the VWF/FVIII ratio in these patients if GrM cleaves VWF in vivo." (PMID 21909423, 2011).
Splenomegaly (2 papers, 2015 to 2025). Abnormal increased size of the spleen. "Bevacizumab could prevent CALI and splenomegaly through inhibition of VWF-rich platelet thrombus formation." (PMID 26580395, 2015). "To further test this hypothesis, we assessed other PH surrogates, including splenomegaly, PLT, and VWF on top of 2D‐SWE‐SSM and 2D‐SWE‐SSM/LSM ratios across aetiologies." (PMID 40884085, 2025). "Plasma levels of VWF:Ag increased with the number of chemotherapy among patients with splenomegaly (P = 0.016 at 3 months, P = 0.006 at 5 months), but not among patients without splenomegaly." (PMID 26580395, 2015). "Plasma VWF:Ag levels at 2, 4 and 5 months of patients with splenomegaly were significantly higher than those of patients without splenomegaly." (PMID 26580395, 2015). "In addition, plasma VWF:Ag and AST levels increased after chemotherapy in patients with splenomegaly (n = 9), but not in patients without splenomegaly (n = 14)." (PMID 26580395, 2015).
thalassemia (2 papers, 2024 to 2025). An inherited blood disorder characterized by a decreased synthesis of one of the polypeptide chains that form hemoglobin. "A total of six articles investigated the levels of vWF in thalassemia patients and healthy individuals." (PMID 40332500, 2025). "Several factors may account for the variability in the vWF expression observed among thalassemia patients." (PMID 40332500, 2025). "Accordingly, this systematic review and meta-analysis aims to explore the levels of endothelial biomarkers, including ICAM-1, VCAM-1, E-selectin, P-selectin, vWF, EMPs, NO, NOS, ADMA, and ET-1, in both thalassemia patients and healthy individuals." (PMID 40332500, 2025). "The pooled analysis of the vWF outcome showed no significant increase in thalassemia compared to the control group." (PMID 40332500, 2025).
varices (2 papers, 2020 to 2025). "Both comparing cases to controls and stratifying cases by disease severity revealed this considerable increase: those with advanced fibrosis and varices had significantly higher VWF antigen titers (P < 0.05)." (PMID 40764410, 2025).
Varicose veins (2 papers, 2015 to 2022). Enlarged and tortuous veins. "Some inflammatory and prothrombotic markers (e.g., IL-6, TNF-α, vWF, and PAI-1) has been reported to be significantly elevated in varicose veins." (PMID 35498031, 2022). "Because the MILAN study lacked data on Von Willebrand factor levels, monocyte percentage, varicose veins, and hospital admission within the past 3 mo (which were strong predictors in the derivation cohort), we adjusted our restricted model." (PMID 26554832, 2015).
vascular hemophilia (2 papers, 2023 to 2025). "In conclusion, the development of vascular hemophilia is closely associated with mutations in the vWF gene." (PMID 40277561, 2025). "Previous studies have shown that the cause of some vascular hemophilia is due to the inability of the A2 structural domain in vWF to undergo a conformational change in a patient as compared to a normal human." (PMID 40277561, 2025). "Von Willebrand factor (VWF), a glycoprotein synthesized and secreted by vascular endothelial cells and megakaryocytes, has been early identified to be associated with vascular hemophilia, and is perceived as a marker of endothelial cell damage." (PMID 37415610, 2023).
vascular malformation (2 papers, 2017 to 2025). A non-neoplastic disorder that is the result of defects of vascular morphogenesis. "In addition, a loss of VWF in ECs results in enhanced and dysfunctional angiogenesis, which is consistent with the clinical observations that in some patients with VWF disease vascular malformations can cause severe gastrointestinal bleeding." (PMID 29333215, 2017).
vitamin B12 deficiency (2 papers, 2022 to 2025). A disease characterized by low serum levels of vitamin B12, either inherited or acquired. "Vitamin B12 deficiency results in higher overall leukocyte levels, indirectly reducing VWF content in thrombi." (PMID 40625905, 2025). "Our study found that vitamin B12 deficiency raises overall leukocyte levels, leading to a reduction in VWF content in thrombi, which is closely linked to poor early prognosis." (PMID 40625905, 2025).
Waldenström's macroglobulinemia (2 papers, 2019 to 2022). "High VWF levels were found to be associated with a lower than 5-year survival and worse outcomes after first-line therapy independently of the international scoring system in Waldenstrom’s macroglobulinemia." (PMID 35327035, 2022).
acute cholangitis (1 paper, 2023). Cholangitis that is both sudden in onset and of a relatively short duration. "Our previous study reported that VWF:Ag/ADAMTS13:AC was associated with the severity of acute cholangitis and DIC score." (PMID 36829443, 2023).
acute GVHD (1 paper, 2022). "Soluble levels of vWF and TNFRI at day 7 post-transplant could positively predict the development of acute GVHD in majority of patients who (90%) expressed higher than cut-off levels of these markers." (PMID 36505438, 2022).
alcoholic liver diseases (1 paper, 2011). A disorder caused by damage to the liver parenchyma due to alcohol consumption. "In cirrhotic liver tissue and even tissue from patients in early stages of alcoholic liver diseases, VWF immunostaining shows positive cells predominantly at the scar–parenchyma interface, within the septum, and in the sinusoidal lining." (PMID 21526182, 2011).
amyloidosis (1 paper, 2024). A disorder characterized by the localized or diffuse accumulation of amyloid protein in various anatomic sites. "A role for CLU that affects basolateral VWF secretion may be directionally consistent with other associated roles for CLU in angiogenesis, amyloidosis and neointimal hyperplasia, as these processes are more likely to affect the basolateral surface than the plasma surface of ECs." (PMID 38363768, 2024).
angiomyolipoma (1 paper, 2014). A neoplasm with perivascular epithelioid cell differentiation often associated with tuberous sclerosis. "vWF can bind to endothelial and fibroblastic regions of the ECM, therefore, it is possible that there is a similar phenomenon occurring with vWF in that it is largely depositing in the LAM cystic regions, as well as potentially in the angiomyolipomas seen in LAM patients." (PMID 25133674, 2014).
Angiosarcoma of the bone (1 paper, 2024). "Angiosarcoma of the bone is also immunopositive for vascular endothelial markers such as CD31, CD34, von Willebrand factor (vWf), and factor VIII-related antigen." (PMID 39463621, 2024).
Arterial stenosis (1 paper, 2017). Narrowing or constriction of the inner surface (lumen) of an artery. "In arterial stenosis as in atherosclerotic injury, a 90% reduction in arterial cross section would similarly increase shear stress on tethered VWF and could cause thrombosis." (PMID 28831047, 2017).
ascending aortic aneurysm (1 paper, 2015). "In this rare but challenging case we report on the successful excision and repair of an ascending aortic aneurysm following adequate VWF/FVIII factor concentrate replacement using Haemate-P." (PMID 25960895, 2015).